IL13 (interleukin 13)
Diseases named in the same sentence as IL13 in open-access papers (continued):
Sharing a sentence is not in itself a finding about the gene and the disease.
asthma (continued). "In eosinophil-dominant severe asthma, anti-IL-4Rα mAb, which blocks both IL-4 and IL-13 signaling, strongly reduced acute exacerbations and increased lung function." (PMID 32326200, 2020). "IFN-γ causes reductions in type 2 innatelymphoid cell (ILC2) expansion and IL-13 expression thereby blocking the progressionof asthma-like phenotype." (PMID 32520202, 2020). "Nonetheless, elevation of IL-6 is also correlated with elevated level of IL-13 and increased in asthma patients." (PMID 32624703, 2020). "IL-13, an asthma-related cytokine, is capable of reducing miR-140-3p to cause an increase in CD38 expression." (PMID 33121100, 2020). "In recent years, clinical drugs have been developed to improve the symptoms of asthma with potential therapeutic effects on IL-4, IL-5, and IL-13 expression levels." (PMID 32244835, 2020). "ILC2 is differentiated from ILC3 in response to activation of TLR2 and produces IL-5 and IL-13, which plays vital role in initiating and promoting immune response among asthma patients, and leads to the accumulation of eosinophils in BALF." (PMID 32600285, 2020). "The eosinophil count; protein expression of TGF-β1, TβR1, and Smad1; and percentages of CD3+γδT and IL-13+CD3+T cells were significantly lower in the M. vaccae nebulization group than in the asthma control group (P < 0.01)." (PMID 32834825, 2020). "IL-13 has been shown to induce asthma symptoms including airway hyper-responsiveness, increased total serum IgE, and increased mucus production in murine models." (PMID 32724101, 2020). "Accordingly, we observed that the gene expression of both IL4 and IL13 were significantly upregulated in the lungs of human asthma patients as compared to those from healthy donors." (PMID 32477356, 2020). "While the anti-inflammatory effects of IL13 prevent lipopolysaccharide-induced lethality and IgG immune complex-induced lung injury in vivo, the proinflammatory function of IL13 in conjunction with IL4 play a key role in the pathophysiology of asthma." (PMID 33506093, 2020). "Maternal supplementation with B. breve M-16V during pregnancy and breastfeeding changed the composition of gut microbiota; some genera correlated with several features of asthma including mucin score and Th2 cytokines including IL-5 and IL-13 in lungs." (PMID 32915886, 2020). "The percentages of CD3+ gamma delta T cells and IL-13+CD3+T cells were significantly lower in the mycobacterium nebulization group compared to the asthma group (P < 0.01)." (PMID 32834825, 2020). "IL-13 has become a therapeutic aim for many diseases, including asthma, idiopathic pulmonary fibrosis, ulcerative colitis, and other IL-13 over-expressing diseases." (PMID 33327639, 2020). "Using IL-13 TG mice, we found that chronic lung inflammation induces alterations in the gut microbiota, suggesting a relationship between the lung-gut axis and asthma." (PMID 33046682, 2020). "It has been demonstrated that IL-33 receptor knockout decreases the airway inflammatory response but induces the persistence of IL-5+ IL-13+ type 2 innate lymphocytes to maintain certain characteristics of asthma." (PMID 32793232, 2020). "During asthma, there is a hyperactivity of Th2 responses, in which the cytokines of the type 2 immunity, such as IL-4, IL-5, and IL-13 promote the harmful inflammatory events in the airways." (PMID 33087044, 2020). "Both in vitro and in vivo studies have demonstrated a strong link between TSLP expression and the production of IL-4, IL-5, and IL-13, which are central in the development of a T2 phenotype in asthma." (PMID 33255348, 2020). "A study showed that asthma remission is associated with genes related to Th2-mediated inflammation, such as IL1RL1-, IL18R1-, and IL-13." (PMID 32292784, 2020). "Previous experiments showed that Majie cataplasm was an effective approach to mitigate asthma airway remodeling and had the potential to regulate Th2 cytokines of IL-5 and IL-13." (PMID 32489402, 2020).
asthma (continued). "Our results are consistent with IL-13 as a therapeutic target for asthma and suggest the potential for improved efficacy if treatment is targeted towards specific genetic subgroups." (PMID 32724101, 2020). "There was a report that ILC2s were a major production source of Il-5 and IL-13 in an OVA-induced asthma mouse model." (PMID 32397396, 2020). "IL-13 (+) ILC2 increased in the circulation of asthma patients and was at a level that correlated with the severity of asthma." (PMID 33265990, 2020). "Airway subepithelial fibrosis is observed in mouse models after IL‐13 overexpression and in patients with T2 biomarker‐high asthma." (PMID 32909660, 2020). "Other than histamine, estrogen mediated production of IL-5 and IL-13 from mediastinal lymph nodes has also been observed in an animal model of asthma." (PMID 33574813, 2020). "Accordingly, asthma induction also significantly decreased Treg-associated IL-10 and TGF-β production while significantly increasing Th2-associated IL-4, IL-5, and IL-13 production and Th17-associated IL-17 production (p < 0.05)." (PMID 33072079, 2020). "These phenomena are accompanied by Th2 cell activation and release of various cytokines (IL-4, IL-5, and IL-13) and chemokines (eotaxin), which are involved in the development of asthma." (PMID 32605045, 2020). "STAT6 is activated by IL-4 and IL-13 and plays a predominant role in the immune system including clearance of helminthic parasites as well as the pathogenesis of allergic disorders like asthma, food allergies, and atopic dermatitis." (PMID 32431691, 2020). "Evidence suggests that β2AR dysfunction can manifest in an inflammatory milieu due to inflammatory cytokines associated with severe asthma and airway remodeling such as TGF-β1, IL-13, and TNF-α." (PMID 33032603, 2020). "Using computational analysis, the authors then found that 31 genes were the targets of these miRNAs, including important genes in asthma pathogenesis such as IL13 and IL5RA." (PMID 33488613, 2020). "An earlier study also reported that fucoidans isolated from U. pinnatifida sporophylls attenuated the Th2 response via suppressing Th2 cytokines (IL-4, IL-5, IL-13) in an OVA-induced mouse model of asthma." (PMID 32580518, 2020). "The clinical indications amenable to anti-IL-13 vaccination based on documented action of anti-IL-13 MAbs to date include atopic dermatitis, subgroups of asthma, and eosinophilic esophagitis." (PMID 32294982, 2020). "To study the effect of Tespa1 on STAT6 pathway, we detected the changes in IL-4 and IL-13 in the BAL of asthmatic mouse model, and the results showed that IL-4 and IL-13 in Tespa1−/− mice significantly increased compared with those in the WT asthma group." (PMID 33228696, 2020). "In fact, these results are in agreement with another study where RSV (100 mg/kg body weight) was found to reduce IL-5 and IL-13 expressions in mice with OVA-induced asthma." (PMID 33013379, 2020). "Most patients with concomitantly elevated levels of sputum eosinophils, periostin, and TSLP also had also increased IL-4 and IL-13 concentrations (6/7 patients for both cytokines, which represents 50% of the asthma group)." (PMID 33203095, 2020). "Mature ILC2 is known to produce Th2-type cytokines (IL-4, IL-5, IL-9, and IL-13) involved in the initiation of an adaptive immune response in asthma." (PMID 32395125, 2020). "The cytokine IL-13 is considered a central effector of allergic asthma which is both necessary and sufficient to induce key features of asthma such as eosinophilic inflammation, mucus production, and airway hyperresponsiveness." (PMID 33046682, 2020). "IL-13 is a cytokine produced by Th2 cells and plays an important role in inflammation related to asthma, atopic dermatitis and atopic eczema." (PMID 33302378, 2020). "Asthma is a chronic inflammatory airway disease in which interleukin-4 (IL-4), IL-13, and TNF-α are involved." (PMID 32139393, 2020).
asthma (continued). "Along with TH2 cytokines, including IL-13 and IL-5, COX-2 has been implicated in asthma pathogenesis." (PMID 33022979, 2020). "Later, high levels of serum periostin proved to be a reliable and promising companion biomaker for identifying a subgroup of severe type-2-immunity-driven asthma patients responding to anti-IL-13 biologics." (PMID 32296705, 2020). "Increased expression of CD146 in the airway epithelial cells of asthma patients was recently discovered, and IL-13 (a type 2 inflammatory cytokine) regulates the expression and function of CD146 in airway epithelial cells." (PMID 32793232, 2020). "Our previous findings that the increased BSM contractility observed in the mouse model of allergic asthma were reproduced by IL-13, one of the asthma-related cytokines, suggest that IL-13 is key for the induction of AHR." (PMID 33121100, 2020). "There was a significant increase in IL-13 levels in the asthma group compared to the control group (50.5 ± 1.85 vs. 40.13 ± 0.31 pg/mL, p = 0.000)." (PMID 31942829, 2020). "In T2-high asthma, airway inflammation is driven by the release of interleukin-4 (IL-4), interleukin-5 (IL-5) and interleukin-13 (IL-13)." (PMID 33352823, 2020). "In the case of rs1800925 and rs20541, the main finding in Asian and some Caucasian populations is with asthma severity and changes in the serum levels of IL-13." (PMID 32366038, 2020). "The exogenous administration of MaR1 (1 ng/mouse) to experimental animals during the allergic phase of asthma results in the decrease in eosinophils number in bronchoalveolar lavage, IgE, IL-5 and IL-13 levels and the increase in TGF-β concentration." (PMID 31216723, 2019). "Collectively, the results derived from different experimental models indicate that IL-13 plays an important role in the development of several aspects of asthma." (PMID 31866859, 2019). "IL-13-induced asthma resulted in changes of lung AQP expression pattern that differed from the one obtained after ovalbumin treatment." (PMID 30397774, 2019). "Other groups have previously detected cells expressing both markers, in a context of GC hyper/metaplasia induced by Sendai virus infection or after IL13 treatment and in asthma." (PMID 31558434, 2019). "Another cytokine whose concentration in BALF was reduced by NT treatment is IL-13, regarded as one of the most crucial cytokines in the initiation and exacerbation of asthma in humans." (PMID 31614422, 2019). "Some data also suggest that HBoV- and B19V-specific IL-13 immune responses contribute to respiratory symptoms in patients with asthma." (PMID 31086415, 2019). "IL-13 is increased in asthma and other airway diseases contributing to chronic inflammation, which increases reactive oxygen species (ROS) in airway epithelial cells in an autophagy-dependent fashion." (PMID 32082074, 2019). "The exposure of allergens in asthma induces the release of pro-inflammatory cytokines, such as IL-5 and IL-13, and ultimately induces eosinophilic airway inflammation and increases in inflammatory mediators." (PMID 30991656, 2019). "The Der p-induced asthma model was associated with increased AHR and bronchial wall thickening, elevated serum IL-19, IL-13, IgE levels, BALF IgA levels, increased immune cell infiltration, and tissue IL-33 and CCL11 in the lungs." (PMID 31114590, 2019). "As asthma control progresses, the expression of IL-13 by ILC2 cells moves gradually closer to normal levels." (PMID 31737687, 2019). "IL-13+ ILC2 were increased in the circulation of asthmatic patients with levels correlating with asthma severity." (PMID 31866859, 2019). "IL-13 is a pro-inflammatory interleukin in asthma, which, similarly to our study, was increased in BALF in the allergic model and reduced after treatment with dexamethasone." (PMID 31779093, 2019). "Drugs targeting the T2 cytokines IL-4 and IL-13 also appear to play a role in reducing exacerbations in patients with severe asthma." (PMID 31395050, 2019).
asthma (continued). "Cytokines such as IL-2, IL-12p40, and IL-13 increased in the present study and reduced by the hybrid are documented to be important mediators of asthma." (PMID 31779093, 2019). "Many randomized controlled trials (RCTs) have showed promising results when treating uncontrolled asthma with anti-IL-13 monoclonal antibodies." (PMID 30703143, 2019). "Group 2 consists of the anti-IL-4Rα antibody, anti-IL-5 antibody, anti-IL-13 antibody, anti-IL-9 antibody, and anti-IL-17 antibody, which are the investigational drugs for asthma." (PMID 31284537, 2019). "In this review we analyze the biological and immunological effects of IL-13 in the context of experimental models of asthma and in asthmatic patients." (PMID 31866859, 2019). "Since IL-13 is a crucial regulator of refractory asthma, it has been identified as a potential therapeutic target for patients with uncontrolled asthma." (PMID 30703143, 2019). "Increased circulating and sputum IL-5 and IL-13-producing ILC2s were detected in severe asthma compared to mild asthma patients." (PMID 31443563, 2019). "A simplistic explanation is that individual blockade of IL-4 or IL-13 is insufficient to inhibit the complex orchestration of allergic inflammation and clinical consequences in severe asthma." (PMID 31866859, 2019). "Contribution to asthma exacerbations are also the case for RSV as IL-13 is believed to be a mediator of viral pathogenesis driving pulmonary eosinophilia via the IL-33/ST2 pathway." (PMID 30759882, 2019). "A disintegrin and metalloproteinase-33 (ADAM-33), TGF-β, vascular endothelial growth factor, matrix metalloproteinase-9 (MMP-9), IL-5, IL-13, and IL-14 are key mediators involved in airway remodeling in asthma." (PMID 31284537, 2019). "Major databases were searched for randomized controlled trials comparing the anti-IL-13 treatment and a placebo in uncontrolled asthma." (PMID 30703143, 2019). "Inflammation triggers asthma pathophysiology via pro-inflammatory cytokines such as tumor necrosis factor α (TNFα) and interleukin 13 (IL-13)." (PMID 32010691, 2019). "IL-13 exposure of airway epithelial cells from donors with asthma-induced, long-lasting modification of DNA methylation." (PMID 31513433, 2019). "Those with T2-high asthma on genetic profile were found to have increased IL-13, IL-5, eosinophils, and mast cells as well as more atopy." (PMID 31294006, 2019). "Pooled analysis of these individual studies can provide comprehensive information to objectively evaluate the potentiality of anti-IL-13 antibodies for the management of uncontrolled asthma." (PMID 30703143, 2019). "Serum IL-31 levels were significantly elevated in patients with asthma and correlated positively with Th2 type cytokines IL-5 and IL-13, asthma severity or total serum IgE." (PMID 30647024, 2019). "Studies on asthma animal models already revealed that this drug is able to reduce the IL-13-mediated development of the disease, including features like AHR, goblet cell hyperplasia, and eosinophil degranulation and accumulation." (PMID 30744098, 2019). "Increased Th2 responses are clearly involved in the onset of asthma and other atopic conditions because IL-4 and IL-13 are required for IgE synthesis and IL-5 is necessary for the recruitment of eosinophils." (PMID 31195744, 2019). "The data from these two Phase II trials suggested that tralokinumab would only be effective in severe asthma when there was evidence of IL-13 activation." (PMID 31315668, 2019). "A systematic review published in 2016 assessed the efficacy of anti-IL-13 antibodies in patients with mild to severe asthma." (PMID 30703143, 2019). "IL-13 is involved in Th2 inflammation and has been identified as a possible therapeutic target in the treatment of asthma." (PMID 31866859, 2019). "In our study, DA-treated mice exhibited a significantly lower number of inflammatory cells in BALF than OVA-induced asthma model, and lower levels of IL-5 and IL-13." (PMID 30991656, 2019).
asthma (continued). "In Der p 2 stimulation, substantial IL-5 and IL-13 levels were detected in most patients with asthma but not in healthy controls; IL-5 production was detectable in all patents with asthma, and IL-13 was detectable in 10 of the 12 patients with asthma." (PMID 31861989, 2019). "IL-5 and IL-13, which are secreted mainly by Th2 cells and group 2 innate lymphoid cells, play important roles in the pathophysiology of asthma." (PMID 31861989, 2019). "Sputum eosinophils and serum periostin are biomarkers that have been proposed for defining which children with asthma will respond to anti-IgE, anti-IL-5, or anti-IL-13 asthma treatment." (PMID 31294006, 2019). "Targeting this pathway through the inhibition of cytokines (IL-4 and IL-13) and their receptors, JAKs or STATs, has been shown to have a therapeutic effect on asthma pathology." (PMID 31284537, 2019). "In the 2017 GINA guideline, anti-IL-13 therapies haven’t been recommended to be add-on treatments for asthma." (PMID 30703143, 2019). "Immunologically, type 2 cytokines (specifically interleukin [IL]-4, IL-5, and IL-13) are recognized as playing a substantial pathobiological role in asthma." (PMID 31151443, 2019). "We also found that only RV-C-infected children with pre-existing asthma had elevated levels of Th2 cytokine IL-13." (PMID 31703379, 2019). "Improvement in FEV1 has been observed in patients with asthma with a high serum periostin levels or detectable sputum IL-13 levels following the administration of MoAbs against IL-13." (PMID 31861989, 2019). "Increased IL-5 and IL-13 expression has been found in allergen-challenged bronchoalveolar lavage fluid cells of patients with asthma." (PMID 31861989, 2019). "In patients affected by asthma, natural killer (NK) cells and type 2 innate lymphoid cells (iLC2) are involved in the containment of eosinophil and antigen independent IL-13 expression, respectively." (PMID 30979024, 2019). "Interleukin-13 (IL-13) is a mediator of allergic inflammation and different diseases including asthma." (PMID 31164999, 2019). "Dupilmab, however, has shown efficacy in treating a wide array of Th2 dependent diseases including AD and asthma, likely through modulation of IL-4 and IL-13’s interaction with immune cells." (PMID 31261951, 2019). "In mouse models, asthma—and especially allergic asthma—are induced by two different treatments: ovalbumin and IL-13 treatment." (PMID 30397774, 2019). "Th2 cells release various proallergic inflammatory cytokines, such as IL-4, IL-5, IL-13, and GM-CSF, which activate basophils and eosinophils and increase mucus secretion in the airway in patients with asthma." (PMID 31284537, 2019). "Considering the individual relevance of IL-4 and IL-13 in the pathogenesis of asthma, these results are surprising and intriguing." (PMID 31866859, 2019). "Lebrikizumab, administered SC, potentially improves lung function and symptom control in asthma by binding to IL-13, neutralizing its functional activities." (PMID 31395084, 2019). "We went on to investigate the influence of maternal atopic diseases, such as asthma, and AD on gestational IL-13 concentrations and the development of behavioral abnormalities in their offspring." (PMID 31428082, 2019). "The third analyzed antibody Fv fragment is binding interleukin-13 (IL-13), which is a member of the growth-hormone-like cytokine family and plays a central role in the development of asthma." (PMID 31803187, 2019). "Patients with T2-high asthma have eosinophilia and other signs of type 2 inflammation including high levels of IL-4 and IL-13." (PMID 31866859, 2019). "It seems that IL-13 is vital in induction of asthma through stimulation of chronic inflammation, eosinophilic infiltration, reversible airway narrowing and airway hyperresponsiveness (AHR)." (PMID 31569687, 2019). "Increased IL-13 expression in asthma was confirmed by IL-13 mRNA overexpression and by ex vivo stimulation of sputum T cells." (PMID 31866859, 2019).